SMAD3 (SMAD family member 3)
Diseases named in the same sentence as SMAD3 in open-access papers (continued):
Sharing a sentence is not in itself a finding about the gene and the disease.
renal fibrosis (continued). "Besides, TGF-β/Smad3 is also revealed to suppress HDAC4 and E-Cadherin expression to accelerate renal fibrosis by miR-29 and miR-200, respectively." (PMID 32587662, 2020). "In the present study, we aimed to investigate whether SSR could alleviate renal fibrosis by regulating NLRP3 inflammasome and Sirt1/Smad3 deacetylation pathway." (PMID 31118021, 2019). "Inhibition of Smad3 and/or JNK signaling activities prevented down-regulation of PGC-1α in tubular epithelial cells and up-regulation of PGC-1α in myofibroblasts during FA-induced renal fibrosis and inflammation." (PMID 31447676, 2019). "However, the relationship between Smad3 signaling and CB2R expression during renal fibrosis development is unclear." (PMID 29789558, 2018). "Smad3 could bind to the promoter region of integrin β1 and then mediated EMT and subsequent renal fibrosis." (PMID 29928474, 2018). "We found rhubarb extracts suppressed TGF-β/Smad3-mediated renal fibrosis by reducing the TGF-β1, transforming growth factor-β receptor I (TGF-β RI), transforming growth factor-β receptor II (TGF-β RII), Smad2, p-Smad2, Smad3, p-Smad3, and Smad4, meanwhile increased Smad7." (PMID 30271345, 2018). "Inhibiting Smad3 activation and nuclear translocation blocks EMT and renal fibrosis." (PMID 29928474, 2018). "Therefore, repression of the expression or activity of Smad3 will inhibit TGF-β1 signaling pathway, which should be helpful for the prevention and treatment of renal fibrosis." (PMID 27853248, 2016). "TGF-β1, a central mediator in renal fibrosis, through Smad3, but not Smad2, to exert its fibrotic activities on GMCs." (PMID 27010029, 2016). "The MMT process occurred predominantly within M2-type macrophages and was regulated by TGF-β/Smad3 signalling as deletion of Smad3 in the bone marrow compartment of GFP+ chimeric mice prevented the M2 macrophage transition into the MMT cells and progressive renal fibrosis." (PMID 26684242, 2016). "In summary, miR-21 contributes to renal fibrosis through multiple alterations in cell metabolism, the regulation of signaling pathways, like Akt and/or ERK/MAPK pathways and targeting Smad7 protein, a negative regulator of TGF-β1/Smad3 signaling." (PMID 27610006, 2016). "Our results indicate that AAT could be a potential therapeutic agent to inhibit the pathway of renal fibrosis, at least partly, through the suppression of TGF-β/Smad3 signaling." (PMID 27607429, 2016). "In particular, the activation of Smad3 plays an important role in various processes including cell growth, differentiation, apoptosis, and tissue repair, and Smad3 serves as a key mediator of the TGF‐β signaling leading to renal fibrosis." (PMID 24973329, 2014). "RvD1 administration reduced endothelial injury, Smad3 linker T179 and S208 activation and renal fibrosis without inhibition of Smad3 C-terminal phosphorylation." (PMID 24391884, 2013). "In addition, JNK has previously been shown to phosphorylate the Smad3 linker region, and blockade of JNK signalling inhibits renal fibrosis in the obstructed kidney." (PMID 24391884, 2013). "Thus, deletion of Smad3 is capable of preventing ANG II-mediated cardiac remodeling and renal fibrosis." (PMID 23301086, 2013). "In summary, DMF attenuated renal fibrosis via the Nrf2-mediated inhibition of TGF-β/Smad3 signaling in an ARE-independent manner, suggesting that DMF could be used to treat renal fibrosis." (PMID 23056222, 2012). "Our study revealed that Glce deficiency in renal tubular cells promoted TGF‐β/Smad pathway activation predominantly associated with TGFBR1 rather than Smad3, however, inhibition of TGF‐β/Smad pathways partially relieved renal fibrosis in Glce‐/‐ mice after UUO." (PMID 40788059, 2025).
renal fibrosis (continued). "Regarding DN, in streptozotocin (STZ)-induced DN models, mice lacking Smad3 were found to avoid renal fibrosis, including glomerular basement membrane (GBM) thickening and excessive extracellular matrix (ECM) production, although the suppression of albuminuria was consistently observed." (PMID 39431155, 2024). "In renal fibrosis, interestingly, although Smad2 shares a high degree of structural similarity to Smad3, overexpression of Smad2 attenuated TGF-β1-induced Smad3 phosphorylation and collagen I matrix, indicating that Smad2 works antagonistically to Smad3 in the progression of renal fibrosis." (PMID 38152335, 2023). "Studies have indicated that TGF-β1 can activate Smad2 and Smad3, which then activate myofibroblasts, leading to excessive production of extracellular matrix (ECM) and inhibition of ECM degradation, thereby inducing renal fibrosis and ultimately chronic renal failure." (PMID 35734171, 2022). "Regarding the mechanism of RRR against renal fibrosis, some studies have shown that its nephroprotective effect was to reduce the expressions of TGF-β1, TGF-β receptor I (TGF-β RI), TGF-β RII, Smad2, p-Smad2, Smad3, p-Smad3, and Smad4, meanwhile increasing Smad7 (Zhang ZH." (PMID 35924053, 2022). "Mechanistically, several preliminary studies have revealed that SKI alleviated CKD and renal fibrosis by inhibiting pro-inflammatory cytokines such as interleukin-6, interleukin-1β, and tumor necrosis factor-α (TNF-α) expression and modulating TGF-β1/Smad3 and JAK2/STAT3 signaling pathways." (PMID 35002735, 2021). "Arid2-IR shares a similar mechanism with Ptprd-IR that overexpression of Arid2-IR may promote TGF-β1-, IL-1β-induced NF-κB-driven inflammation without affecting TGF-β/Smad3-mediated renal fibrosis." (PMID 34054586, 2021). "Additionally, the treatment of an obstructed kidney with short hairpin lncRNA-Arid2-IR (shRNA) blunted NF-κB-driven renal inflammation without any effect on TGF-β1/Smad3-mediated renal fibrosis." (PMID 32295041, 2020). "Relative to Smad3, the function of Smad2 in renal fibrosis is not fully elucidated." (PMID 32613000, 2020). "Pterostilbene, also mentioned in this review, suppresses the activation of TGF-β1/Smad3 and proto-oncogene tyrosine-protein kinase Src/Signal transducer and activator of transcription 3 (Src/STAT3) signaling pathway as to decrease sUA level and alleviate renal fibrosis in hyperuricemic mice." (PMID 33568990, 2020). "However, unlike the diverse role of Smad2 and Smad3 in renal fibrosis, blocking Smad2 or Smad3 is capable to attenuate AKI." (PMID 31754396, 2019). "Therefore, in addition to using it for inhibiting serine proteinases, our findings suggest that AAT treatment could be used to inhibit renal fibrosis, at least partially, through modulating TGF-β/Smad3 pathway." (PMID 27607429, 2016). "In addition, recent studies have shown a role for adiponectin/AMPK and JAK3/STAT6 signaling pathways in the development of experimental renal fibrosis and in collagen production by cultured mouse monocytes, providing new potential therapeutic targets in addition to TGF-β/Smad3 signaling." (PMID 27906172, 2016). "Based on these observations, we therefore hypothesized that the combination of AA and NG may produce a better therapeutic effect on renal fibrosis by more effectively correcting the imbalance of TGF-β/Smad signaling, namely upregulation of Smad7 while suppressing Smad3." (PMID 26474462, 2015). "In the present study, we also found that addition of AA was capable of blocking Smad3 phosphorylation and renal fibrosis by upregulating Smad7 without altering expression of Smad3, identifying AA as a Smad7 agonist to inhibit Smad3 signaling by inducing Smad7 transcription." (PMID 26474462, 2015). "Moreover, recent studies also demonstrated TGF-β/Smad3-mediates renal fibrosis by upregulating microRNA-21 in both diabetic and non-diabetic kidney diseases." (PMID 24646636, 2014).
renal fibrosis (continued). "In addition, SMAD2 and SMAD3 knockout augmented the production of inflammatory factor (TNFα and IL-6), while SIRT2-mediated NLRP3 deacetylation protects against inflammation, indicating SIRT2 may be a more attractive target to improving renal fibrosis." (PMID 37777567, 2023). "However, in Pkd1RC/RC kidneys, nintedanib treatment did not change SMAD3 activity, an important component of TGFβ-signaling pathway and a contributor to renal fibrosis, as suggested by no change in pSMAD3/SMAD3 ratio, when compared with vehicle treatment (Supplemental 4A, B)." (PMID 34650051, 2021). "In our recent study, Smad3 KO in db/db mice were found to be protected from the development of diabetic kidney injury, characterized by the normal levels of urinary albumin excretion and serum creatinine without any evidence for renal fibrosis and inflammation." (PMID 33369170, 2021). "Finally, DMF suppressed unilateral ureteral obstruction (UUO)-induced renal fibrosis and α-SMA, fibronectin and type 1 collagen expression in the obstructed kidneys from UUO mice, along with increased and decreased expression of Nrf2 and phospho-Smad3, respectively." (PMID 23056222, 2012). "In this study, we found that mice lacking Smad3 were protected against CRP-exacerbated kidney injury, including progressive renal fibrosis and inflammation." (PMID 34671208, 2021). "In this study, we demonstrate that PR-619 suppresses renal fibrosis and reduces Smad4 expression but not the expression of TGF-β receptors, Smad2, or Smad3, in mice with unilateral ureteral obstruction (UUO), a well-established mouse model of renal fibrosis." (PMID 30114247, 2018). "We recently demonstrated that Smad3, but not Smad2, is the key transcription factor responsible for TGF-β-mediated renal fibrosis." (PMID 23301086, 2013). "Furthermore, Klotho exerts its influence on renal fibrosis via downstream signaling pathways, including but not limited to the transforming growth factor-β1 (TGF-β1)/Smad3 and wnt/β-catenin pathways." (PMID 39325739, 2024). "Interestingly, unlike PP1 inhibiting Src to block Smad3 and STAT3 signaling pathways, Fyn-mediated renal fibrosis is mediated by the non-Smad signaling pathway, that is, caused by activation of STAT3, and Smad3 and AMPK signaling transduction are not essential in this process." (PMID 35883540, 2022).
breast carcinoma (234 papers, 2005 to 2026). "In primary breast tumors, YAP suppresses SMAD family member 3 (Smad3) activity, enhancing the survival and self-renewal of tumor-initiating cells, which increases the risk of breast cancer recurrence and metastasis." (PMID 40673277, 2025). "Our further results revealed that the family member ZNF8, a novel Smad3 cofactor, was associated with the prognosis of lung metastasis in patients with breast cancer." (PMID 39225541, 2024). "As described in the previous sections, ZNF8 is a novel Smad3 interaction protein and was associated with the lung metastasis of breast cancer." (PMID 39225541, 2024). "In the present study, we showed that THBS1 expression was positively associated with TGF-β1 and Smad3 in clinical breast cancer specimens by use of public database." (PMID 33912465, 2021). "The only association detected was a significant increase in phospho-SMAD3 expression in luminal A breast cancers compared to HER2+ breast cancers." (PMID 33888841, 2021). "Mutations in the SMAD3 linker strongly enhanced TGF-β-induced responses in breast cancer cells and increased tumorigenesis in the liver." (PMID 34360888, 2021). "THBS1 expression was positively associated with TGF-β1 (r = 0.11, p <0.001) and Smad3 (r = 0.39, p <0.001) in breast cancer." (PMID 33912465, 2021). "The underlying mechanism of action of FOXM1 in breast cancer involves sustained activation of SMAD3/SMAD4 activity, which further induces TGF-β-dependent EMT and promotes metastasis." (PMID 31554904, 2019). "Smad3 point mutation rate in breast cancer is 0.4% (4 mutations out of 952 cases analyzed) (TCGA provision data)." (PMID 27588495, 2016). "Although the possible effect of the SNP on SMAD3 function is still unclear, it is believed that the effects on both breast cancer and generalized OA susceptibility are mediated through the TGF-β signaling pathway." (PMID 24852296, 2014). "Loss of WWOX expression leads to significant upmodulation of SMAD3 transcriptional activity leading to overexpression of multiple gene targets associated with breast cancer progression." (PMID 24330518, 2013). "The overexpression of SMAD3 in a breast cancer cell line has been shown to cause cell cycle arrest, while in SMAD3−/− mammary epithelial cells, both TGF-beta-induced growth inhibition and apoptosis are lost." (PMID 22646717, 2012). "Smad3 mutation has been identified in one colorectal cancer cell line, and is infrequent in human colon cancer tissues and breast cancers." (PMID 22204491, 2011). "Two candidate genes that are of potential interest in clinical genetics of breast cancer are SMAD3 and SMAD4, encoding the key signaling transduction proteins of the Transforming Growth Factor-β (TGF-β) pathway." (PMID 21835029, 2011). "SMAD3 expression levels in breast cancers harboring variants (BC-VAR; n = 3) were significantly higher compared to CO-VAR (n = 11; P = 0.038) and CO-REF (n = 12; P = 0.035)." (PMID 21835029, 2011). "Furthermore, we found that SMAD3 K53/K333 methylation levels were highly consistent and associated with poor survival in breast cancer." (PMID 35085106, 2022). "SMAD3 methylation is upregulated in breast cancer and associated with worse overall survival." (PMID 35085106, 2022). "Moreover, quantitative analysis suggested that Sp1 and Smad3 caused an additive effect on EGFR expression in breast cancer cells." (PMID 29215776, 2018). "Modulation of Smad3 levels are much more frequent events than mutations in breast cancer." (PMID 27588495, 2016). "However, other research finds that CTGF and PAI-1, the downstream target gene of TGF-β/Smad3 signaling, is correlated with a high risk of metastasis in breast cancer." (PMID 24427302, 2014). "We next asked what biological activities might underlie the tumor-suppressive effects of TGF-β/Smad3 in breast cancer." (PMID 24890385, 2014).
breast carcinoma (continued). "Most notable was the evidence that the SMAD3 gene, which encodes a key regulatory protein in the transforming growth factor beta signalling pathway, may contribute to increased risk of breast cancer in BRCA2 mutation carriers." (PMID 21114847, 2010). "In summary, we hypothesize that the progressive loss of WWOX expression in advanced breast cancer contributes to deregulating the TGFβ pathway and, more importantly, may explain some of the pro-metastatic effects resulting from TGFβ/SMAD3 hyperactive signaling in advanced breast cancer." (PMID 24330518, 2013). "Since loss of WWOX expression increases with breast cancer progression and it behaves as an inhibitor of SMAD3 transcriptional activity these observations may help explain, at least in part, the paradoxical pro-tumorigenic effects of TGFβ signaling in advanced breast cancer." (PMID 24330518, 2013). "Several lines of evidence suggest that SMAD3 may be involved in breast cancer susceptibility." (PMID 21835029, 2011). "In addition, SMAD3, like many breast cancer susceptibility genes, is in direct protein-protein interaction with BRCA1 as it counteracts BRCA1-mediated DNA repair and its MH2 domain has recently been shown to associate with BRCA1 during oxidative stress response." (PMID 21835029, 2011). "Studies of breast cancer found that HNF3α inhibited the nuclear translocation of Smad3 (a key transcription factor downstream of the TGF‐β signaling pathway) by suppressing its binding with the nuclear import receptor importin‐7." (PMID 40091743, 2025). "Further, the fluorescence imaging demonstrated that the SMAD2‐silenced mouse suffered more serious breast cancer bone metastasis in the femur, tibia, and vertebra, however, the SMAD3‐silenced mouse presented a contrast result." (PMID 39947253, 2025). "Immunofluorescence imaging revealed an enhanced fluorescent signal of phosphorylated Smad2/Smad3 in breast cancer cells after 3oc treatment, and these fluorescent signals were mainly located in the nucleus." (PMID 39786928, 2025). "In patients with breast cancer in the advanced stages of metastasis, SMAD family member 3 (SMAD3) has been implicated in inducing MDM2 transcription via its second promoter." (PMID 40191734, 2025). "Endoglin depletion has been shown to reduce cancer-promoting pathways, including TGF-β/SMAD3/VEGF and MAPK/p38 signaling, induced by breast cancer-causing phthalates." (PMID 40072060, 2025). "The involvement of Wnt ligands in TGF-β–induced invasiveness has been previously reported for breast cancer cells, where Wnt7a and Wnt7b were found to be induced by the Smad3–JunB cooperative transcriptional activation." (PMID 38141763, 2024). "Reduced interaction between CCL2 and CCR2 on breast cancer cells can hinder their migration and survival, possibly through diminished activation of Smad3 or MAPK signaling." (PMID 38360633, 2024). "Our studies confirmed that ZNF8, which interacts with Smad3, plays a critical role in the regulation of breast cancer metastasis via TGF‐β through SMYD3." (PMID 39225541, 2024). "The transforming growth factor‐β (TGF‐β) pathway plays a vital role in breast cancer metastasis, in which Smad3 is the key mediator and performs specific functions by binding with different cofactors." (PMID 39225541, 2024). "TGFβ-induced EGFR upregulation in breast cancer cells can be mediated by the canonical SMAD3 and ERK/SP1 signaling pathways." (PMID 39468555, 2024). "TGF-β or EGF on HER2-overexpressed breast cancer cells can induce SMAD3 phosphorylation, and CEACAM6 expression level is upregulated after treatment, but this correlation is not obvious in HER2-negative breast cancer cells." (PMID 38796667, 2024). "Overall, the study identifies a novel cofactor of TGF‐β/Smad3 that promotes lung metastasis in breast cancer and introduces potential therapeutic strategies for the early management of breast cancer lung metastasis." (PMID 39225541, 2024).